HIF1A (hypoxia inducible factor 1 subunit alpha)
Diseases named in the same sentence as HIF1A in open-access papers (continued):
Sharing a sentence is not in itself a finding about the gene and the disease.
diabetes (continued). "Therefore, the increased production of AGEs in the diabetes-exposed Hif1a+/− heart may represent an increased risk for vascular and myocardial damage in association with impaired contractility, inflammation, and endothelial dysfunction." (PMID 29753320, 2018). "In diabetes, excessive oxidative stress and metabolic toxicity destabilize HIF-1α and decrease its transcriptional activity." (PMID 41596300, 2026). "Together, these findings support the conclusion that hypobaric hypoxia improves angiogenesis and myogenesis post-injury in diabetes by enhancing HIF-1α signaling." (PMID 41596300, 2026). "Increased methylglyoxal (MGO) in diabetes makes it more difficult for HIF‐1α to dimerize and simultaneously bind to the co‐activator (p300)." (PMID 41508422, 2026). "A comprehensive review of scientific literature, including PubMed, Science Direct, EMBASE, Google Scholar, and Web of Science, was conducted to explore the role of hypoxia and HIF-1α in the intersection of type 2 diabetes mellitus and endometrial cancer." (PMID 39996906, 2025). "Under the heightened oxidative stress induced by diabetes, HIF-1α contributes to reducing oxidative damage in testicular cells by regulating antioxidant enzyme expressions, including SOD and GPx." (PMID 40867634, 2025). "In the published literature, elevated serum HIF-1α concentration showed a significant correlation with the progression of nephropathy in Saudi patients with type 2 diabetes mellitus (T2DM)." (PMID 39648258, 2025). "Understanding these pathways offers critical insights into the pathogenesis of diabetes-induced testicular damage and establishes a theoretical foundation for targeting HIF-1α as a potential therapeutic strategy." (PMID 40867634, 2025). "With the rising global prevalence of diabetes, the role of HIF-1α in diabetes-induced testicular injury has garnered increasing research interest." (PMID 40867634, 2025). "The role of autophagy in microvascular remodeling in diabetes is actively discussed, particularly regarding interactions with HIF1α, mTOR, and the Bnip3/FoxO3a axis." (PMID 41169477, 2025). "While HIF-1α modulators such as Roxadustat and Vadadustat are being tested for anemia and kidney-related complications in diabetes, their application in reproductive disorders remains limited." (PMID 40867634, 2025). "Collectively, the protective role of PI-3K/Akt-mediated HIF-1α regulation was highlighted in diabetes-induced injury, positioning this pathway as a promising therapeutic target." (PMID 40867634, 2025). "For therapies targeting HIF-1α to be effective, patients with EC and diabetes should be tested for prognostic markers such as HIF-1α expression levels." (PMID 39996906, 2025). "HIF-1α is a key regulator of metabolic processes and directly contributes to the development of insulin resistance (IR) and diabetes mellitus." (PMID 41155523, 2025). "In conclusion, a comprehensive understanding of HIF-1α’s mechanistic role in diabetic testicular damage provides valuable insights into the pathogenesis of diabetes-related reproductive disorders and offers new avenues for therapeutic intervention." (PMID 40867634, 2025). "Xue and colleagues demonstrated in a transgenic diabetes mouse model that cardiomyocyte-specific HIF-1α overexpression increased myocardial capillary density and prevented diabetes-mediated cardiac hypertrophy and glycolytic metabolism remodeling." (PMID 41303720, 2025). "Diabetes alters renal oxygen supply, impairing physiological adaptations including the activation of HIF-1α and metabolic reprogramming necessary for maintaining adenosine triphosphate (ATP) production." (PMID 41353143, 2025). "In diabetes, elevated glucose levels induce HIF-1α activity, leading to a switch from oxidative to glycolytic metabolism and a Warburg-like metabolic phenotype." (PMID 41296433, 2025). "The expression and activity of HIF-1α can link the metabolic dysregulation in diabetes to cancer progression." (PMID 39996906, 2025).
diabetes (continued). "In diabetes-induced testicular cell apoptosis, HIF-1α plays a dual role by facilitating cellular adaptation to hypoxia and protecting cells from apoptosis." (PMID 40867634, 2025). "Future research focusing on the mechanistic pathways and translational potential of HIF-1α is expected to provide novel theoretical insights and therapeutic targets for the management of diabetes-related male infertility." (PMID 40867634, 2025). "This complexity highlights the need for further research to unravel the complex relationship between HIF-1α and diabetes." (PMID 39996906, 2025). "The literature discussed in this review was identified through a systematic search of PubMed, Web of Science, and Scopus databases up to June 2025 using keywords such as ‘HIF-1α’, ‘diabetes’, ‘testicular injury’, ‘male fertility’, and ‘hypoxia signaling’." (PMID 40867634, 2025). "Our findings that Lir significantly modulated HIF-1α levels under both normoglycemic and hyperglycemic conditions suggest that the drug may influence cellular responses associated with hypoxic stress, potentially contributing to improved cellular resilience in the context of diabetes." (PMID 41155741, 2025). "In contrast, BMAL1 overexpression appears to provide renal protection in diabetes by promoting mitophagy via the HIF-1α/BNIP3 signaling pathway." (PMID 40594206, 2025). "Among the molecular mediators linking diabetes and reproductive dysfunction, HIF-1α plays a particularly pivotal role." (PMID 40867634, 2025). "In a pathophysiological setting, an increased Hif-1α expression seems to be beneficial, as in a murine model of diabetes the cardiac specific overexpression of Hif-1α protects against diabetic induced cardiomyocyte hypertrophy and fibrosis." (PMID 39820339, 2025). "The regulation of Hif1α is highly crucial since this molecule has key functions in various medical circumstances such transplantation and diseases, especially in diabetes, tumor biology, and tumor angiogenesis." (PMID 40739162, 2025). "Despite the relative hypoxia which can be present in diabetic tissues, the stability of HIF-1α protein is compromised in people with diabetes, and also in pre-clinical models of diabetes." (PMID 39769216, 2024). "DNA methylation levels of PSMA6, PSMB5, and HIF1A genes were positively correlated with the duration of diabetes, HbA1c, and albuminuria in certain study groups." (PMID 38927561, 2024). "In the pancreatic β-cells of mouse models with diabetes, HIF-1α protein expression is significantly increased, accompanied by a decrease in SIRT1 expression." (PMID 39408861, 2024). "At E18.5, the most pronounced deficit in cardiac sympathetic innervation was detected in Hif1aCKO embryos exposed to maternal diabetes, indicating a long-lasting synergistic effect of Hif1a deletion and the diabetic environment." (PMID 38505753, 2024). "In contrast, in BIN mice, which lack β-cell HIF1α, there was 100% diabetes induction within 15 weeks of MLDS." (PMID 39769216, 2024). "This research looked at how a specific process in bone-forming cells, called the hypoxia-inducible factor-1 alpha (HIF-1α) pathway, affects sugar breakdown and diabetes." (PMID 38945950, 2024). "In this study, we measured HIF-1α and survivin levels in the serum of patientswith diabetes as potential biomarkers and investigated their potential relationshipswith the severity of retinopathy." (PMID 38656026, 2024). "The hyperglycaemia of diabetes impairs the cellular response to hypoxia by destabilizing HIF-1α protein and inhibiting its transcriptional function." (PMID 39769216, 2024). "Canonical pathway analysis of all the genes that were identified to be differentially rhythmic in control and diabetes included phototransduction, glucose metabolism, HIF1a signaling, ER stress, DNA damage and cell cycle checkpoints to be affected." (PMID 38039846, 2024).
diabetes (continued). "Further analysis of senescence-related targets recognized the HIF-1α/autophagy pathway as the core anti-senescence mechanism of JCYSTLF in diabetic kidneys." (PMID 38720731, 2024). "In line with our observations, prior research has reported a high presence of HIF-1α-positive β-cells in diabetic mouse models, and PX-478 treatment has demonstrated efficacy in enhancing β-cell function in individuals with diabetes." (PMID 39408861, 2024). "Here, we investigate the role of β-cell HIF-1α in β-cell death and diabetes after exposure to multiple low-dose streptozotocin (MLDS)." (PMID 39769216, 2024). "Hif1α is also activated in response to high glucose via ChREBP, which aligns with an increased risk of developing RCC in diabetes mellitus but makes the finding of increased tumorigenesis in ChREBP-KO mice more surprising." (PMID 39518998, 2024). "According to the results, the anti-senescence effect of JCYSTLF in diabetes is closely related to the upregulation of HIF-1α." (PMID 38720731, 2024). "For the differentially expressed lncRNAs identified, MIR7-3HG, LINC01116, HIF1A, MEG3, XIST, NEAT1, and HHLA3 have been previously associated with some form of diabetes and diabetes-associated complications." (PMID 38326874, 2024). "Dysfunctions of hypoxia-inducible factor (HIF-1α) in diabetes have been indicated to deteriorate wound closure, whereas stabilization of HIF-1α has been shown to improve wound healing and osteoarthritis." (PMID 38139019, 2023). "Islets proteomics demonstrated that DFEs in the OI vs. STZ groups were significantly enriched in diabetes, insulin secretion, insulin resistance, and in the HIF1-α, mTOR, and MAPK signaling pathways." (PMID 36918798, 2023). "A recent study suggested that treating MSCs with estradiol promotes the migration of cells in cultured MSCs and a cell therapy model of diabetes via adjustment of critical mediators of cell trafficking like hypoxia-inducible factor-1a (HIF-1a)." (PMID 37009006, 2023). "We showed that, similar to many other diabetic organs, diabetes increased the expression of HIF-1α in Sertoli cells." (PMID 36778206, 2023). "It showed that diabetes leads to significant decreases of HIF-1α and ANG1 in ECs of spinal cord after SCI." (PMID 37215981, 2023). "This study characterized how the combination of HIF-1α deficiency and streptozotocin (STZ)-induced diabetes affects the cardiac sympathetic nervous system and heart function of adult animals." (PMID 37072781, 2023). "Recent research suggested that HIF-1α was increased in peripheral nerve fibers in patients with diabetes, and it implied the relationship between HIF-1α and diabetic peripheral neuropathy." (PMID 36017378, 2022). "Patients with diabetes have decreased bone regeneration capacity and cells cultured in hyperglycaemic conditions (25 and 50 mM) have been demonstrated to have an impaired HIF-1α pathway and a consequent reduced ability to respond to hypoxic conditions." (PMID 35977987, 2022). "Other pharmacology and molecular docking analyses have revealed that P. vulgaris (in both plant and prepared medicine forms) affects HIF-1α and the apoptosis signaling pathway in sleep disorders, thyroiditis, and diabetes mellitus." (PMID 35444541, 2022). "Conceivably, the partnership between WWOX and HIF1α is crucial in the regulation of tumor metabolism and diabetes pathology." (PMID 36271927, 2022). "Studies have also shown that HIF-1α expression is high in patients with diabetes and kidney injury and that angiotensin-II increases the expression of HIF-1α in renal tubular epithelial cells in vitro." (PMID 35188068, 2022). "On the contrary, glucose enhances ROS production and HIF-1α expression, leading to podocyte injury and fibrosis in diabetes mice." (PMID 36297636, 2022). "TSC22D3 inhibits hypoxia- and diabetes-induced galectin-1 expression due to hypoxia and diabetes by disrupting the stability of the HIF-1α protein." (PMID 36466094, 2022).
diabetes (continued). "Set7_1a induces the accumulation of HIF-1α, especially after preincubation with homocysteine (Hcy), an elevated factor in diabetes, to upregulate the expression of HIF-1α target proteins in cellulo and in vivo." (PMID 35859119, 2022). "Contrary to what we wrote, HIF-2α plays a protective role against the development of diabetes (of which HIF-1α is involved in the pathogenesis)." (PMID 33567688, 2021). "The result showed that the HIF-1α expression was drastically decreased in DFU subjects when compare to that of diabetes subjects." (PMID 34293021, 2021). "In diabetes, depleted HIF-1α has severe pathological consequences including impaired wound healing, poor recovery from cardiac ischemia, and pancreatic β cell dysfunction." (PMID 34426491, 2021). "We have shown that HDL rescues diabetes-impaired angiogenesis via the classical HIF-1α/VEGFA signaling axis." (PMID 34483928, 2021). "Surprisingly, the effect of hyperglycemia/diabetes on HIF-1α expression in epithelial cells of renal proximal tubules is still poorly understood." (PMID 34948094, 2021). "It is well known that the expression of VEGF-A is regulated by the activity of HIF-1α, which is stabilized under hypoxia and diabetes." (PMID 33709000, 2021). "In murine diabetes models, complex 1a induced the accumulation of HIF-1α and the activation of HIF-1α-driven genes that are important for angiogenesis, including VEGFR, SDF-1α and SCF." (PMID 34099651, 2021). "The wound healing process in diabetes is impaired due to hyperglycemia induced oxidative stress and reduced activity of HIF-1α, followed by decreased neovascularization and tissue formation." (PMID 34356303, 2021). "Liraglutide restores the lost cardioprotective effects of remotepreconditioning in diabetes by increasing the expression of Nrf2,H2S and HIF-1α." (PMID 33656046, 2021). "Increased HIF1 expression is associated with overall poorer survival in breast cancer patients, and several studies directly or indirectly implicate HIF1-α in the diabetes-breast cancer crosstalk." (PMID 34225729, 2021). "Conversely, in eye vascular ECs (VECs) which are prone to inflammatory-driven angiogenesis in diabetes, miR-181c was shown to promote stabilisation of HIF-1α in these cells." (PMID 34483928, 2021). "In the context diabetes, the role of hyperglycemia in the regulation of the HIF1α signaling is controversial and remains the subject to much debate." (PMID 33520443, 2021). "HIF1α is both an anti-inflammatory transcription factor and one of the major mediators of impaired wound healing in diabetes." (PMID 32210958, 2020). "We found that HIF-1α-Tg BMDCs induced a suboptimal cytotoxic response compared to WT BMDCs, and these data are consistent with the limited induction of diabetes observed earlier." (PMID 33382742, 2020). "The transcript of Hif-1α was not changed in diabetic mice, but the expression of HIF-1α protein was higher accompanied by the lower expression of PHD2 in kidneys from mice with diabetes." (PMID 32444604, 2020). "Our study reports the impairment of retinal vascular endothelial cells by HG or states mimicking diabetes, and Re pretreatment was shown to exert protective effects against DR through the HIF-1α/VEGF signal in the HG-induced retinal vascular injury model." (PMID 32528282, 2020). "Glucocorticoid treatment to mice significantly alleviated diabetes‐induced retinal HIF‐1α and galectin‐1/Lgals1 levels, while increasing TSC22D3 expression." (PMID 32150332, 2020). "In summary, this study confirmed that the increase of MGO content in diabetes can lead to the instability of HIF-1α, which results in the delay of wound healing due to the damage of the HIF-1α signal pathway and its downstream effects." (PMID 33392167, 2020). "In contrast to our findings with HIF-1α-Tg BMDCs, HIF-1α KO BMDCs were found to promote an enhanced cytotoxic response compared to WT, although diabetes incidence was comparable to WT." (PMID 33382742, 2020).
diabetes (continued). "Mice with proximal tubule‐specific knockout of HIF‐1α (PT‐HIF‐1α−/− mice) were generated, and diabetes was induced in these mice by streptozotocin (STZ) injection." (PMID 32975326, 2020). "We also verified that treatment with glucocorticoids reduced diabetes‐induced HIF‐1α protein up‐regulation." (PMID 32150332, 2020). "Available literature shows that HIF-1α is involved in regulation of metabolic processes and mediates development of IR and diabetes mellites." (PMID 33013447, 2020). "In the present study, mice with proximal tubular cell‐specific genetic ablation of HIF‐1α were generated, and mice were induced to diabetes by streptozotocin (STZ) injection." (PMID 32975326, 2020). "Hearts of Hif1-α heterozygous mice with exogenously-induced diabetes had decreased levels of apoptosis and altered gene expression profiles of angiogenic genes." (PMID 32816039, 2020). "In contrast, RIP-gp mice receiving CpG-matured HIF-1α-Tg BMDCs showed reduced incidence of diabetes compared to mice immunized with wildtype BMDCs, while HIF-1α KO CpG-stimulated BMDCs had similar diabetes induction compared to WT." (PMID 33382742, 2020). "VEGF is one of the most important downstream targets of HIF-1α, and its expression is known to be impaired in diabetes." (PMID 32455604, 2020). "There is much evidence supporting the concept that HDL augments diabetes-impaired HIF-1α activity and VEGFA expression, resulting in the rescue of angiogenesis both in vitro and in vivo." (PMID 32455604, 2020). "Hyperglycemia in diabetes has a complex repressive effect on the stabilization and transactivation of HIF-1α, precluding its optimal reaction to hypoxia." (PMID 31214621, 2019). "The HIF-1α function is repressed in diabetes, which contributes to an inappropriate reaction to hypoxic injury." (PMID 31214621, 2019). "Patients with the HIF-1A Pro582Ser polymorphism, which is more resistant to the repressive effect of hyperglycemia, may therefore have a better adaptation and responses to the retinal hypoxia even from an early period of diabetes that will preclude the progression to severe DR." (PMID 31214621, 2019). "Limb ischemia is a complication of diabetes mellitus, and administration of HIF-1α activators has been considered as a potential treatment." (PMID 30837602, 2019). "Diabetes and ROS induce local hypoxia with upregulated mRNA expression levels of proapoptotic proteins, HIF-1α, and AMPK phosporylation, which activate cell death VEGF and production." (PMID 31814880, 2019). "In vivo and in vitro pharmacological HIF hydroxylase inhibition restored HIF-1α accumulation and improved post-ischemic functional recovery in diabetes." (PMID 30175272, 2018). "The combination of Hif1a insufficiency and exposure to diabetes in utero leads to the accelerated development of cardiac LV dysfunction." (PMID 29753320, 2018). "Hif1a+/− mice exposed to only 5 weeks of diabetes develop decreased fractional shortening, undetectable in control mice." (PMID 30158902, 2018). "In diabetes, this correlation presumably resulted from stimulating the recovery of blood flow, similar to the induction of HIF-1α in the ischemic limb." (PMID 29549140, 2018). "Correspondingly to decreased macrophage infiltration, we found a significantly reduced level of TNFR2 in the LV of diabetes-exposed Hif1a+/− mice." (PMID 29753320, 2018). "This is mediated by elevated FAs in diabetes suppressing succinate accumulation during hypoxia, and increasing succinate concentrations can override this inhibitory effect on HIF-1α stabilization." (PMID 30175272, 2018). "Our genome-scale transcriptome analyses clearly identified a set of pathophysiological processes affected by the maternal diabetes exposure and Hif1a+/− genotype in the LV of offspring." (PMID 29753320, 2018). "For the first time to our knowledge, the current study demonstrated that Hif1a haploinsufficiency significantly worsens the cardiac function of the diabetes-exposed offspring." (PMID 29753320, 2018).